PNPO (pyridoxamine 5'-phosphate oxidase)
Diseases named in the same sentence as PNPO in open-access papers (continued):
Sharing a sentence is not in itself a finding about the gene and the disease.
breast invasive ductal carcinoma (2 papers, 2019 to 2021). "Additionally, it has been shown that high expression of PNPO was associated with clinical stages and metastasis in breast invasive ductal carcinoma, but we found that PNPO was more likely a protective factor in BRCA patients from Kaplan–Meier plotter databases." (PMID 35127701, 2021). "The protein expression of PNPO in human breast invasive ductal carcinoma was examined, while mRNA expression of PNPO in BRCA was tested in Kaplan–Meier plotter databases." (PMID 35127701, 2021). "This study aims to evaluate the biological function and the regulatory mechanism of PNPO in human breast invasive ductal carcinoma (IDC)." (PMID 30982780, 2019). "PNPO could be regulated by the MALAT1/miR-216b-5p/PNPO axis in the development of human breast invasive ductal carcinoma." (PMID 35127701, 2021).
Cirrhosis (2 papers, 2021 to 2026). A chronic disorder of the liver in which liver tissue becomes scarred and is partially replaced by regenerative nodules and fibrotic tissue resulting in loss of liver function. "Given emerging reports of cirrhosis in people with PNPO deficiency, it is possible that other patients may need liver transplantation." (PMID 41527660, 2026). "PNPO deficiency could also lead to hepatic cirrhosis, which may be associated with apparent epigenetic activation of purinergic signaling in hepatic stellate cells." (PMID 35127701, 2021).
Developmental delay (2 papers, 2022 to 2023). "PNPO (pyridoxamine 5′-phosphate oxidase): Pyridoxamine 5'-phosphate oxidase deficiency is a rare metabolic disorder leading to seizures, developmental delay, and intellectual disability." (PMID 37927689, 2023). "Developmental delay is one common symptom manifested by PNPO-deficient patients, raising the question of whether specific developmental impairments lead to seizures." (PMID 35217610, 2022).
encephalopathies (2 papers, 2020 to 2025). "Human genetic studies have identified severe PNPO mutations as causative for neonatal encephalopathies, and PNPO has recently been recognized as one of 16 major risk genes for adult epilepsy." (PMID 40093095, 2025).
Epileptic spasm (2 papers, 2021 to 2022). A sudden flexion, extension, or mixed extension-flexion of predominantly proximal and truncal muscles that is usually more sustained than a myoclonic movement but not as sustained as a tonic seizure. "In a genetic study of epileptic spasms, there was 1 case who presented a mutation of PNPO." (PMID 33748042, 2021).
hyperprolinemia type 2 (2 papers, 2021 to 2023). Hyperprolinemia type 2 is an autosomal recessive proline metabolism disorder due to pyroline-5-carboxylate dehydrogenase deficiency. "PLP depletion is the main pathophysiological mechanism for different inborn errors of metabolism, including ALDH7A1 deficiency, PNPO deficiency, PLP binding protein deficiency, hyperprolinemia type II, hypophosphatasia, and glycosylphosphatidylinositol (GPI) anchor synthesis defects." (PMID 36980111, 2023).
lymph node metastasis (2 papers, 2017 to 2019). "Analyses showed that the expression level of PNPO in IDC was not significantly correlated with clinicopathological features such as age, lymph node metastasis, tumor size, histological grade, and tumor stage." (PMID 30982780, 2019).
Multiple Myeloma (2 papers, 2021 to 2025). "Pyridoxine‐5'‐phosphate oxidase (PNPO), a target of celastrol, promotes cell proliferation and osteoclast differentiation via exosomes in multiple myeloma (MM)." (PMID 39656865, 2025).
neonatal encephalopathy (2 papers, 2017 to 2024). "PNPO deficiency is responsible of severe neonatal encephalopathy, responsive to pyridoxal-5′-phosphate (PLP) or pyridoxine." (PMID 29379851, 2017).
uveal melanoma (2 papers, 2021). A melanoma derived from melanocytes of the uveal tract. "A high level of PNPO predicted good OS in OV (p = 0.047), while a high level of PNPO predicted poor OS of UVM (uveal melanoma) by Kaplan–Meier survival analysis (p = 0.0261)." (PMID 35127701, 2021). "The abnormal expression of PNPO could predict the survival outcome of patients with esophageal carcinoma (ESCA), kidney renal clear cell carcinoma (KIRC), prostate adenocarcinoma (PRAD), ovarian serous cystadenocarcinoma (OV), and uveal melanoma (UVM)." (PMID 35127701, 2021).
acute myeloid leukemia (1 paper, 2021). Acute myeloid leukemia (AML) is a group of neoplasms arising from precursor cells committed to the myeloid cell-line differentiation. "On the contrary, PNPO was decreased in ACC (adrenocortical carcinoma), KIRC (kidney renal clear cell carcinoma), LAML (acute myeloid leukemia), and TGCT (testicular germ cell tumors) compared to control tissues." (PMID 35127701, 2021).
anemia (1 paper, 2014). A reduction in the number of red blood cells, the amount of hemoglobin, and/or the volume of packed red blood cells. "Other than seizures, patients with PNPO deficiency also exhibit metabolic disorders, such as hypoglycemia, acidosis, and anemia because PLP is a co-factor required for more than 100 enzymes that function in amino acid metabolism, gluconeogenesis, immune system, and neurotransmitter synthesis." (PMID 24739647, 2014).
brain tumor (1 paper, 2021). "The staining of PNPO was also strong in prostate cancer (n = 6) and brain tumor (n = 6) tissues, but not in their adjunct tissues or normal tissues in this tissue array." (PMID 35127701, 2021).
breast invasive carcinoma (1 paper, 2021). "The highest gene alteration rate of PNPO appears for pan-cancer patients with uterine corpus endometrial carcinoma, uterine carcinosarcoma, breast invasive carcinoma, pancreatic adenocarcinoma, and mesothelioma with amplification (>2%) as the primary type using the cBioPortal database." (PMID 35127701, 2021).
clear cell carcinoma (1 paper, 2017). "Our data are consistent with a cohort of data sets found in Oncomine, which PNPO mRNA was higher in serous, mucinous, endometrioid and clear cell carcinomas compared with the normal ovary." (PMID 29238081, 2017). "Our study provides the evidence of PNPO overexpression in the tumour tissues of human EOC, including serous, mucinous, endometrioid, transitional cell and clear cell carcinoma." (PMID 29238081, 2017).
deficiency (1 paper, 2015). "These disorders include autosomal dominant GTPCH deficiency, TH deficiency, PTPS deficiency, DHPR deficiency, PDE-ALDH7A1 and PNPO deficiency combining inherited monoamine and pyridoxine metabolism disorders." (PMID 25758715, 2015). "In one patient with PNPO deficiency (10%), mildly elevated CSF threonine and 3-OMD levels as well as response to pyridoxal-5-phosphate therapy led the confirmation of the diagnosis." (PMID 25758715, 2015). "Autosomal dominant GTPCH deficiency, TH deficiency, PTPS deficiency, DHPR deficiency, PDE-ALDH7A1 and PNPO deficiency combining inherited monoamine and pyridoxine metabolism disorders were identified in our study cohort." (PMID 25758715, 2015). "In this group, 5 patients (83%) had a treatable inherited neurotransmitter disorders including GTPCH deficiency, PTPS deficiency, DHPR deficiency, PDE-ALDH7A1 and PNPO deficiency." (PMID 25758715, 2015).
developmental and epileptic encephalopathy (1 paper, 2026). An epilepsy associated with developmental impairment that may be due to either the underlying etiology or the superimposed epileptic activity, or both. "Pyridoxal-5′-phosphate (PLP) is in most patients the effective treatment for pyridox(am)ine-5′-phosphate oxidase (PNPO) deficiency, a rare autosomal recessive cause of neonatal-onset developmental and epileptic encephalopathy." (PMID 41429136, 2026).
Fibroadenoma (1 paper, 2019). A benign tumor of the breast characterized by the presence of stromal and epithelial elements. "The expression of PNPO mRNA and protein was higher in breast IDC (malignant tumor) tissues than adjacent normal breast tissues and fibroadenomas (benign tumor) tissues." (PMID 30982780, 2019). "PNPO concentration was higher in patients with IDC than in women without tumor and patients with fibroadenoma." (PMID 30982780, 2019).
germ cell tumours (1 paper, 2017). "By analysis of histological types, we found that PNPO protein expression was significantly associated with surface epithelial malignant tumours compared with sex cord-stromal and germ cell tumours (P < 0.001)." (PMID 29238081, 2017). "Higher levels of PNPO expression were found in surface epithelial malignant tumours rather than sex cord-stromal and germ cell tumours, indicating that the overexpression of PNPO may be EOC specific." (PMID 29238081, 2017).
hepatocellular carcinoma (1 paper, 2026). A malignant tumor that arises from hepatocytes. "In an adolescent with PNPO deficiency, PLP treatment was hepatotoxic and was associated with hepatocellular carcinoma." (PMID 41527660, 2026).
liver cirrhosis (1 paper, 2021). "Collectively, these reports highlight the possibility of PLP‐related liver dysfunction in PNPO‐deficient patient, and hence surveillance for evidence of liver cirrhosis should be part of management of PNPO‐deficient patients receiving PLP." (PMID 32888189, 2021). "Four cases of PNPO deficiency were presented with liver cirrhosis or abnormal liver function test after receiving PLP treatment." (PMID 32888189, 2021).
medulloblastoma (1 paper, 2021). A malignant, invasive embryonal neoplasm arising from the cerebellum. "PNPO was overexpressed in almost all the human cell lines in the CCLE database except the medulloblastoma cell line." (PMID 35127701, 2021).
mesothelioma (1 paper, 2021). A usually malignant and aggressive neoplasm of the mesothelium which is often associated with exposure to asbestos. "We also found that PNPO had a complex regulation with different signaling pathways in MESO (mesothelioma), OV, SARC, and UCEC." (PMID 35127701, 2021).
metabolic epilepsies (1 paper, 2024). "Dietary treatment can compensate for the deficiency, which has been demonstrated in many metabolic epilepsies, including for pyridoxine 5’-phosphate oxidase (PNPO) deficiency-induced epilepsy." (PMID 38351047, 2024).
monoclonal gammopathy of undetermined significance (1 paper, 2025). "PNPO expression was significantly elevated in patients with monoclonal gammopathy of undetermined significance (MGUS, n = 44) and MM (n = 351) compared to normal plasma (NP, n = 22) (p < 0.001)." (PMID 39656865, 2025).
ovarian serous malignant tumour (1 paper, 2017). "Overexpression of PNPO protein in ovarian serous malignant tumour was confirmed by western blot." (PMID 29238081, 2017).
ovarian tumour (1 paper, 2017). "In the present study, PNPO expression in human ovarian tumour tissue and its association with the clinicopathological features of patients with EOC were examined." (PMID 29238081, 2017). "To determine the correlation between PNPO mRNA expression and miR-143 expression in patients with ovarian tumours, we performed a qRT-PCR in ovarian tissues of 14 patients (4 benign, 3 borderline, 7 malignant tumours) and 5 normal controls." (PMID 29238081, 2017). "Following our recent reports that human cystatin B, β-2-microglobulin and cytidine monophosphate kinase are ovarian tumour progression markers and are regulated by TGF-β129–31, we speculate that PNPO may be another EOC biomarker and that it may also be regulated by TGF-β signalling." (PMID 29238081, 2017).
pancreas cancer (1 paper, 2021). "PNPO protein was expressed in pancreas normal and adjacent tissues, while not expressed in pancreas cancer, which was not consistent with its mRNA expression level." (PMID 35127701, 2021).
plasma cell tumors (1 paper, 2025). "We also investigated the impact of PNPO on disease progression using a pristane‐induced model, a well‐established model for spontaneous plasma cell tumors." (PMID 39656865, 2025).
sarcoma (1 paper, 2021). A usually aggressive malignant neoplasm of the soft tissue or bone. "Then, we found that the overexpression of PNPO was significantly associated with tumor status in BLCA and GBM, while the overexpression of PNPO was correlated with tumor-free status in KIRC and SARC (sarcoma)." (PMID 35127701, 2021).
status epilepticus (1 paper, 2023). Status epilepticus is defined as a continuous seizure lasting more than 30 min, or two or more seizures without full recovery of consciousness between any of them. "These advantages were confirmed in cases of PNPO deficiency, where the change from pyridoxine to PLP resulted in seizure aggravation or even the occurrence of status epilepticus in affected children." (PMID 36980111, 2023).
substance abuse (1 paper, 2023). The use of a drug for a reason other than which it was intended or in a manner or in quantities other than directed. "In the current analysis, we found that maternal report of substance abuse in her household during childhood was associated with offspring regional DNAm of PNPO, a protein coding gene involved in the biosynthesis of vitamin B6, which is a co-factor for neurotransmitter synthesis." (PMID 37845746, 2023).
transitional cell carcinoma (1 paper, 2017). A malignant neoplasm arising from the transitional epithelium, usually affecting the urinary bladder, ureter, or renal pelvis. "The immunoreactive staining of PNPO was weak in normal tissues of the ovary and the fallopian tube and benign tumour, moderate in borderline tumour and strong in malignant tumours, including serous, mucinous, endometrioid, clear cell and transitional cell carcinomas." (PMID 29238081, 2017).
cancer (9 papers, 2017 to 2025). A tumor composed of atypical neoplastic, often pleomorphic cells that invade other tissues. "According to the ESTIMATE algorithm, the correlation between PNPO expression and immune-associated cell infiltration also occurred in many types of cancer, including BRCA, KIRC, KIRP, and PRAD." (PMID 35127701, 2021). "The expression of PNPO was related to the infiltration levels of various immune-associated cells in pan-cancer by ESTIMATE algorithm and TIMER database mining." (PMID 35127701, 2021). "The relationship between PNPO expression and immune-associated cells infiltration in pan-cancer was further performed in the TIMER database." (PMID 35127701, 2021). "However, the role of PNPO and the mechanisms underlying the regulation of PNPO in cancer progression, especially in EOC, are unknown." (PMID 29238081, 2017). "The identification of the PLP allosteric site of human PNPO paves the way for the rational design of enzyme inhibitors as potential anti‐cancer compounds." (PMID 38284493, 2024). "The pan-cancer analysis systematically displayed the characteristics of PNPO in multiple aspects, including expression pattern, survival prognosis, genetic mutation, MMR, MSI, TMB, tumor immune microenvironment, signaling pathway, and drug sensitivity." (PMID 35127701, 2021). "PNPO was significantly upregulated in most types of cancer, while it was only found to be downregulated in ACC, KIRC, LAML, and TCGT compared to control tissues." (PMID 35127701, 2021). "Drug metabolism was the most common signaling pathway of PNPO involved in pan-cancer, followed by hematopoietic cell lineage, porphyrin, and chlorophyll signaling pathway." (PMID 35127701, 2021). "We then unearthed the fact that amplification was the most altered frequency of PNPO in pan-cancer using the cBioPortal database." (PMID 35127701, 2021). "Next, the expression of PNPO in pan-cancer was further analyzed through the RNA-seq data of TCGA and GTex databases." (PMID 35127701, 2021). "The protein expression level of PNPO was strongly expressed in both normal and cancer tissues of the liver (n = 5) and kidney (n = 5)." (PMID 35127701, 2021). "We further explored the correlation between the mRNA expression level of PNPO and patients’ clinicopathological features progression in pan-cancer." (PMID 35127701, 2021). "Gene Set Enrichment Analysis (GSEA) was applied to elucidate the biological function of PNPO in pan-cancer." (PMID 35127701, 2021). "This study highlights the multifaceted role of PNPO in pan-cancer, which provides a rationale for targeting PNPO as a novel therapeutic strategy." (PMID 35127701, 2021). "We comprehensively investigated the different expression levels of PNPO in pan-cancer and normal control tissues via The Cancer Genome Atlas (TCGA), Genotype-Tissue Expression (GTEX), and Oncomine databases." (PMID 35127701, 2021). "In order to survey the prognostic assessment value of PNPO in pan-cancer, Cox proportional hazards model and Kaplan–Meier analysis were carried out to evaluate the relationship between PNPO expression and patients’ survival period." (PMID 35127701, 2021). "PNPO was also expressed in a major percentage of certain cancer types, such as BRCA (n = 7), HNSC (n = 3), and UCEC (n = 8) without significant difference." (PMID 35127701, 2021). "From KEGG analysis, we found that drug metabolism is the most common signaling pathway of PNPO involved in pan-cancer." (PMID 35127701, 2021). "This study highlights the multifaceted roles of PNPO in pan-cancer and provides new insights into the candidate effect of PNPO in regulating chemoresistance." (PMID 35127701, 2021). "PNPO was regarded as a high-risk factor for LAML and THYM, while it was a low-risk factor for KIRC of OS prognosis assessment in pan-cancer." (PMID 35127701, 2021). "Further analysis demonstrated that the expression of PNPO is significantly associated with MSI in 14 cancer types and TMB in 4 cancer types." (PMID 35127701, 2021).